RAB7A (RAB7A, member RAS oncogene family)
Diseases named in the same sentence as RAB7A in open-access papers (continued):
Sharing a sentence is not in itself a finding about the gene and the disease.
mood disorder (1 paper, 2020). A cognitive disorder a disturbance in which the person's mood is hypothesized to be the main underlying feature. "Further studies focusing on the association between RAB7A and the different manifestations of mood disorders based on these functions are needed." (PMID 32245436, 2020). "Recently, RAB7A was demonstrated to modulate endoplasmic reticulum stress, which is associated with mood disorders." (PMID 32245436, 2020). "Other functions of RAB7A include growth-factor-mediated cell signalling and lipid metabolism, which are also proposed mechanisms involved in the pathophysiology of mood disorders." (PMID 32245436, 2020).
myocardial infarction (1 paper, 2025). Gross necrosis of the myocardium, as a result of interruption of the blood supply to the area, as in coronary thrombosis. "Rab7a may be activated by multiple mechanisms through a GEF such as Ccz1, reducing TBC1D15 (GAP protein) levels as shown in vitro and in a mouse model of myocardial infarction, or through post-translational protein modifications." (PMID 41024170, 2025).
osteoporosis (1 paper, 2024). A condition of reduced bone mass, with decreased cortical thickness and a decrease in the number and size of the trabeculae of cancellous bone (but normal chemical composition), resulting in increased fracture incidence. "Among these, GAS6, SPP24, RAB7A, and TSP are known to play a role in fibroblast proliferation, angiogenesis, and immune response and may offer insight into the mechanism of osteoporosis." (PMID 39336514, 2024).
ovarian carcinoma (1 paper, 2019). A malignant neoplasm originating from the surface ovarian epithelium. "Recently, it has also been demonstrated that ovarian cancer cells in hypoxic conditions increased their exosome release by upregulating RAB27A and downregulating several protein among which RAB7A, and also by promoting a more secretory lysosomal phenotype with increased CDDP efflux." (PMID 30626032, 2019).
pancreatic adenocarcinoma (1 paper, 2022). "By comparing RAB7A expression in normal specimens in the TCGA and GTEx databases with tumour specimens in the corresponding TCGA database, RAB7A was found to be significantly highly expressed in 28 cancers, including pancreatic adenocarcinoma (PAAD)." (PMID 36261459, 2022).
pneumonia (1 paper, 2021). An acute, acute and chronic, or chronic inflammation focally or diffusely affecting the lung parenchyma, caused by an infection in one or both of the lungs (by bacteria, viruses, fungi, or mycoplasma.). "The Rab7a knockout MSCs were injected into mice with LPS-induced pneumonia, and the lung tissues of the mice were taken at 1 W, 4 W, and 8 W." (PMID 34367295, 2021). "H&E pathological examination showed that the knockout of Rab7a significantly weakened the therapeutic effect of MSCs in mice with LPS-induced pneumonia." (PMID 34367295, 2021).
pulmonary fibrosis (1 paper, 2021). Chronic progressive interstitial lung disorder characterized by the replacement of the lung tissue by connective tissue, leading to progressive dyspnea, respiratory failure, or right heart failure. "Masson staining and α-SMA staining results were consistent with H&E results, indicating that Rab7a knockout attenuates the therapeutic effect of MSCs on LPS-induced pulmonary fibrosis in mice." (PMID 34367295, 2021).
sarcoidosis (1 paper, 2025). Sarcoidosis is a multisystemic disorder of unknown cause characterized by the formation of immune granulomas in involved organs. "In addition, membrane-associated HGFA, ILF3, RAB7A, and RPL18 in alveolar macrophages were proposed as diagnostic biomarker candidates for sarcoidosis 58,59." (PMID 41279897, 2025).
schizophrenia (1 paper, 2023). A major psychotic disorder characterized by abnormalities in the perception or expression of reality. "Here these two proteins, RAB6B and RAB7A, were found altered in the prefrontal cortex in schizophrenia with an interaction with both ACTR1A and DCTN5." (PMID 37033658, 2023). "Our results provide an altered molecular network involved in immune response in the DLPFC in schizophrenia with a central role of RAB7A." (PMID 37033658, 2023). "Thus, our results provide an altered molecular networks involved in immune response in the DLPFC in schizophrenia with a central role of RAB7A." (PMID 37033658, 2023).
serous ovarian cancer (1 paper, 2019). "With the aim to investigate a possible correlation between RAB7A expression and chemotherapy response ex vivo, we have analyzed RAB7A expression in few tumor tissues of patients diagnosed with high grade serous ovarian cancer." (PMID 30626032, 2019).
Stroke (1 paper, 2025). Sudden impairment of blood flow to a part of the brain due to occlusion or rupture of an artery to the brain. "Our data demonstrate that Rab7a-mediated rescue of acute BBB dysfunction after stroke in vivo is not accompanied by changes in Caveolin-1 protein levels or transcellular permeability in vivo, although the inflammatory milieu in stroke increases Cav-1 protein levels in BECs." (PMID 41024170, 2025).
Thyroid adenoma (1 paper, 2022). The presence of a adenoma of the thyroid gland. "Studies of several tumours, such as thyroid adenomas and ovarian/primary peritoneal plasmacytoma, have assessed the expression and function of RAB7A in tumour development." (PMID 36261459, 2022).
triple-negative breast carcinoma (1 paper, 2021). An invasive breast carcinoma which is negative for expression of estrogen receptor (ER), progesterone receptor (PR), and human epidermal growth factor receptor 2 (HER2). "The authors showed that in PTEN-null triple-negative breast cancer, when the phosphomimetic S72E mutant of Rab7A is overexpressed, hence when Rab7A cannot be activated, the degradation of STING is suppressed, and the production of cytokines, such as CCL5, CXCL10 and IFNβ, is aberrantly enhanced." (PMID 34572553, 2021).
type 2 diabetes (1 paper, 2020). "Targeting Rab7a therefore represents a novel potential therapeutic approach to promoting islet survival in type 2 diabetes patients." (PMID 32978479, 2020). "Pharmaceutical Rab7a inhibition may provide a means to promote beta cell survival in the context of metabolic stress and prevent the onset of type 2 diabetes." (PMID 32978479, 2020). "Furthermore, our data demonstrates that inhibition of Rab7a can be used to enhance beta cell growth factor responsiveness and to promote islet survival under conditions of metabolic stress relevant to the conditions that occur in many people with type 2 diabetes." (PMID 32978479, 2020).
cancer (23 papers, 2013 to 2025). A tumor composed of atypical neoplastic, often pleomorphic cells that invade other tissues. "Growth factor deprivation in cancer cells increases the fraction of Rab7a associated with membranes, and Rab7a-GTP (active form) triggers cell death due to degradation of nutrient transporters essential for survival." (PMID 41024170, 2025). "Thanks to this function, RAB7A is also involved in cellular processes linked to cancer, such as apoptosis, cytoskeletal reorganization, and cell migration." (PMID 34066419, 2021). "Conversely, Rab7a inhibition after growth factor withdrawal promotes cancer cell survival due to recycling of transporters to the cell surface." (PMID 41024170, 2025). "TBC1D15 has been identified as a putative Rab7a inactivator (GAP), since it accelerates GTP hydrolysis by Rab7a in vitro and its overexpression disrupts lysosomal morphology and blocks growth factor withdrawal-induced death in cancer cells." (PMID 41024170, 2025). "Rab7a inhibition is critical to prevent degradation of nutrient transporters and support survival in lymphocytes and cancer cells." (PMID 41024170, 2025). "Of note, RAB7A plays a key role in autophagosome maturation 32, 33, and overexpression of RAB7A promotes cancer progression 34-36." (PMID 35813474, 2022). "RAB7A transcript levels were shown to be relatively high in cancer tissues from PAAD patients, according to further investigation." (PMID 36261459, 2022). "Among potential GSDMB interacting cancer and autophagy proteins, some Rab GTPases were found (Rab5C, Rab7A, Rab9A and Rab15)." (PMID 36163066, 2022). "First, we analysed the expression of the core gene RAB7A using the RNA sequencing (RNA-seq) data of PAAD samples from The Cancer Genome Atlas (TCGA) and Genotype-Tissue Expression (GTEx) databases." (PMID 36261459, 2022). "Previously, we demonstrated that RAB7A regulates phosphorylation and assembly of vimentin, a cytoskeletal intermediate filament protein, which is also an important mesenchymal marker of cancer cells." (PMID 34066419, 2021). "We observed reduced expression of RAB7A in pre-chemo cancer samples from R1, R2 and R3 compared to matched post-chemo tissue, while increased RAB7A levels were displayed by patients with complete response to therapy, such as R4 and R5." (PMID 30626032, 2019). "The different impact of RAB7A in cancer progression, probably depending on the cellular context and on other environmental factors, is analyzed below." (PMID 31374919, 2019). "Surprisingly, a high number of chemotherapy cycles (which is one of the marker to define a patient as poor responder) resulted into an increase of RAB7A in post-chemo cancers." (PMID 30626032, 2019). "The aim of this review is to describe the role of RAB7A in cancer progression and in chemoresistance and to illustrate the emerging and preliminary attempts to target RAB7A and late endocytic pathway as a novel strategy to cancer treatment." (PMID 31374919, 2019). "Compared to Rab7a expression of Rab7b was minimal in all tested cancer lines." (PMID 39562548, 2024). "We found that most types of cancers had positive staining for RAB7A." (PMID 36261459, 2022). "According to these definitions RAB7A was described as oncogene or tumor suppressor depending of its capacity to favor tumor progression or to prevent malignant growth, inducing or blocking different aspects within the eight hallmarks of cancer." (PMID 31374919, 2019). "Recently, some studies have reported the role of Rab7a in cancer." (PMID 29769411, 2019). "Vimentin, an indicator of epithelial–mesenchymal transition, is regulated by Rab7a in cancer cells." (PMID 29769411, 2019). "Indeed, for instance, mutations in the RAB7A gene cause the Charcot-Marie-Tooth type 2B (CMT2B) peripheral neuropathy and there are numerous reports in the literature indicating RAB7A as a lead actor of cancer." (PMID 31374919, 2019).
cancer (continued). "With the limitation of the extremely low number of samples, these data suggest that RAB7A expression in pre-chemotherapy cancer tissues may predict response, although studies are warranted on a larger cohort of patients in order to draw definitive conclusions." (PMID 30626032, 2019). "Taken together these data corroborate our hypothesis that Rab7a KO and TPC2 KO exert similar effects on cancer hallmarks and that the effect of Rab7a is mediated through TPC2, as the loss of Rab7a can be largely compensated with TPC2 agonist or overexpression but not vice versa." (PMID 39562548, 2024). "Thus, RAB7A could play a role in cancer cell proliferation and invasion regulating beta-catenin stability through AKT and PAK1." (PMID 34066419, 2021). "Therefore, the interest in the role of RAB7A in cancer progression is increasing." (PMID 34066419, 2021). "In HT1080 and U87MG cancer cells, the CD44s isoform of CD44 predominantly expressed in these cells interacts with Rab7A in the late-endosome/lysosome compartments, reduces levels of the GTP-bound form of Rab7A, and inhibits the Rab7A-mediated EGFR degradation." (PMID 39594667, 2024). "RAB7A-mediated lipophagy increased cellular PUFAs, which enhances RAS-selective lethal 3 (RSL3)-induced ferroptosis in cancer cells." (PMID 38490434, 2024). "ACE2, RAB7A, CCDC22, ATP6AP1, NPC1, and PIK3C3 exhibited a positive relationship with sensitivity of 18 anti-cancer drugs (P < 0.01)." (PMID 35082790, 2021). "Several dynamically regulated Ras-related proteins were identified in this study, including RAB7A and RAN, which were increasingly overexpressed at the whole cell level with increased cancer progression." (PMID 24086712, 2013). "The apparent upregulation of multiple classic cancer pathways, such as RAS, MAPK and PPAR, indicates that these pathways may be important in the regulation of RAB7A in PAAD." (PMID 36261459, 2022). "The CNVs of RAB7A, BIRC5, SERPINE1, and FABP4 were relatively high in most cancers." (PMID 36518255, 2022). "ACE2, RAB7A, PIK3C3, ATP6AP1, NPC1, and ATP6V1A had a negative association with the sensitivity of 16 anti-cancer drugs (P < 0.05)." (PMID 35082790, 2021). "Modulation of Rab7a activity affects a number of disease pathologies including neuropathies and neurodegenerative diseases such as Charcot-Marie-Tooth type 2B, hereditary sensory neuropathy type 1, and Niemann Pick type C1 (NPC1), infectious diseases, and cancer, including melanoma." (PMID 39562548, 2024). "Altogether these results demonstrate that RAB7A regulates AKT and PAK1 kinases, affecting their downstream effectors and the processes they regulate, suggesting that RAB7A could have a role in a number of cancer hallmarks." (PMID 34066419, 2021). "RAB7A expression is reported to both promote and inhibit tumor development and progression, with different effects observed in different cancer types, while RAB27 is reported to promote growth, invasion, metastasis, and chemoresistance in a variety of cancer types." (PMID 31318078, 2020).
tumor (21 papers, 2015 to 2025). "Although RAB7A is associated with tumour progression in multiple tumour types, there are only a few reports in PAAD." (PMID 36261459, 2022). "A forest plot highlighted key oncogenic factors such as SNX5, YBX1, TPM3, and RAB7A, which were significantly associated with poorer survival and may drive tumor progression." (PMID 41031219, 2025). "Moreover, we observed a downregulation of RAB5B and upregulation of RAB7A, two small GTPases closely linked to intracellular transport and tumor progression." (PMID 40080350, 2025). "After that, RAB7A, radiation therapy, histological grade, and residual tumour were all included in multivariate Cox regression, which suggested that they were all independent predictors of poorer OS (P < 0.05)." (PMID 36261459, 2022). "Multifactorial Cox regression analysis showed that high RAB7A expression was an independent prognostic factor for worse OS, in addition to radiotherapy, histological grading and postoperative residual tumour." (PMID 36261459, 2022). "In tumor cell lines, the loss of FLCN resulted in slower endocytic trafficking of EGFR by decreased Rab7A GTP-to-GDP turnover, resulting in prolonged and elevated phosphorylated EGFR and downstream signaling." (PMID 35863698, 2022). "Four independent prognostic factor variables, namely, RAB7A expression, radiation therapy, histological grade and residual tumour, were included in the model." (PMID 36261459, 2022). "A paper published in 2020 by Ritter and colleagues also reported the involvement of Rab7A phosphorylation in tumor progression." (PMID 34572553, 2021). "Based on lentivirus knockdown strategy, we found that Rab7a silencing led to decreased cell viability, growth, cell invasion, and xenografted tumor growth of MDA-MB-231 cells." (PMID 29769411, 2019). "Knockdown of Rab7a induced the apoptosis, cell cycle arrest, and promoted the cell proliferation, growth, invasion, and xenografted tumor development of MDA-MB-231 cells." (PMID 29769411, 2019). "To explore the role of Rab7a knockdown in tumor development, we subcutaneously implanted the shCtrl or shRab7a MDA-MB-231 cells into the nude mice." (PMID 29769411, 2019). "Tumor volume was monitored and the results showed that Rab7a silencing moderately suppressed the tumor development of MDA-MB-231 cells in nude mice." (PMID 29769411, 2019). "FLCN WT significantly increased the GTPase activity of Rab7A compared to the GST vector alone, and there was a trend towards decreased GTPase activity of the tumour-associated mutant form of FLCN (FLCN C9)." (PMID 28656962, 2017). "Rab7A WT, FLCN WT or the tumour-associated FLCN K508R mutant were purified from transfected 293T cells." (PMID 28656962, 2017). "The model includes seven key genes—SNX5, YBX1, GNPD1, RAB32, TPM3, ATP6V0B, and RAB7A—which may be involved in tumor growth, immune escape, and microenvironment remodeling and may serve as potential targets for therapy." (PMID 41031219, 2025). "The high expression levels of RAB7A, PIK3C3, ATP6AP1, ATP6V1A, CCDC22, and NPC1 were significantly associated with lower tumor purity of patients with hematologic cancer LAML, while TMPRSS2, PIK3C3, ATP6AP1, and ATP6V1A expressions were obviously correlated with higher tumor purity of KICH patients." (PMID 35082790, 2021). "In vivo, Rab7a silencing suppressed the xenograft tumor progression of MDA-MB-231 cells." (PMID 29769411, 2019). "Collectively, Rab7a silencing inhibits the tumor development in vivo." (PMID 29769411, 2019). "In vivo, depletion of Rab7a inhibited the xenograft tumor development of MDA-MB-231 cells." (PMID 29769411, 2019). "To ensure that the GAP activity of FLCN is not due to co-purification of other mammalian proteins, we GST-purified FLCN WT protein, or a tumour-associated mutant form of FLCN (FLCN C9) from bacteria and tested their ability to hydrolyse GTP when combined with Rab7A." (PMID 28656962, 2017).